FGFR2 (fibroblast growth factor receptor 2)
Diseases named in the same sentence as FGFR2 in open-access papers (continued):
Sharing a sentence is not in itself a finding about the gene and the disease.
breast carcinoma (continued). "FGFR2 harbours one of the first SNPs to be identified as a breast cancer susceptibility locus by Genome-Wide association studies (GWAS)." (PMID 34830836, 2021). "Taken together, these data demonstrate that FGFR2 activation is positively associated with PD‐L1 expression in breast cancer." (PMID 34514747, 2021). "In conclusion, fibroblast growth factor receptor alterations (e.g., FGFR1 copy number variations and FGFR2 SNPs) influence the risk and prognosis in patients with breast cancer." (PMID 32852708, 2020). "The authors also carried out an analysis of the METABRIC (Molecular Taxonomy of Breast Cancer) dataset and found a 1.8% rate of FGFR2 amplification in breast cancer, associated with a poorer prognosis and resistance to endocrine therapy." (PMID 32852708, 2020). "Fibroblast growth factor receptor 2 (FGFR2), a kind of tyrosine kinases, presented frequent SNPs and point mutations in breast cancer, and these epigenetic changes increased the risk of tumor formation." (PMID 31894857, 2020). "Genetic variant rs3792152 of REV1 is associated with breast cancer risk in Thai women and rs2981582 ofFGFR2(Fibroblast Growth Factor Receptor 2) plays a vital role in the cell proliferation, migration, and apoptosis." (PMID 32487238, 2020). "In breast cancer, high FGFR2 expression is significantly associated with tumor size and metastasis, shorter overall survival and lower disease-free survival rates." (PMID 31987043, 2020). "The FGFR2 gene exhibited a strong association (also with a strong support from RDM) with breast cancer only for the protective haplotype, which includes the major allele from rs2981582." (PMID 33126731, 2020). "Single-nucleotide polymorphisms (SNPs) in FGFR2 locus 10q26 have been reported to have the strongest association with breast cancer risk in genome-wide association studies." (PMID 32852708, 2020). "Genetic variant rs2981582 of FGFR2 has been associated with breast cancer in different women population (Dutch, Arabic, and West Siberia)." (PMID 32487238, 2020). "Certain genetic variants, such as FGFR4 rs1966265 and FGFR2 rs2981578, have also been involved in the outcome of breast cancer patients treated with chemotherapeutic agents." (PMID 33081025, 2020). "In this vein, the Genome-Wide-Association-Studies (GWAS) has ascertained that some SNPs (rs2981582, rs1219648, rs2420946, rs2981579) within the FGFR2 intron 2 are associated with an increased breast cancer risk in postmenopausal women." (PMID 33081025, 2020). "Single nucleotide polymorphisms in intron 2 of the FGFR2 gene are associated with the incidence of breast cancer." (PMID 32432040, 2020). "It has also been reported that in the context of FGFR2 genetic variants and breast cancer, lower FGFR2 expression is associated with increased response to estrogen and these FGFR2 variants are associated with poor prognosis." (PMID 32676501, 2020). "In the largest breast cancer GWAS cohort to date, SNPs near FGFR2 demonstrate association at p < 10−300; these are the smallest p-values across the entire genome." (PMID 30875371, 2019). "Deregulation of FGFR2 contributes to tumor progression and activating mutations in FGFR2 have been found in different types of cancer, like gastric cancer, breast cancer, and endometrial carcinoma." (PMID 31146385, 2019). "Further analysis showed that three breast cancer risk SNPs (rs2981578, rs35054928 and rs45631563) in the FGFR2 locus were responsible for reduced expression of FGFR2, conferred increased estrogen responsiveness and a higher risk of ER-positive IDC." (PMID 31142340, 2019). "High levels of FGFR2 have been associated with gastric cancer 39, 40, oral squamous cell carcinoma 41 and breast cancer 42, 43, and promote the proliferation, invasion, and metastases of tumor cells." (PMID 31523191, 2019).
breast carcinoma (continued). "Over the entire pathway database, 172 pathways containing FGFR2 were tested for association with breast cancer, and 172 were significant at the Bonferroni-corrected threshold according to GBJ." (PMID 30875371, 2019). "A study in Tunisian population reported that subjects with AA genotype of FGFR2 rs2981582 had increased risk of breast cancer." (PMID 31781300, 2019). "One of these variants concerns the oncogene FGFR2, the FGFR2 protein being overexpressed in 5% of breast cancers." (PMID 31413819, 2019). "Review of the breast cancer step-down results illustrates that many seemingly significant sets are completely dependent upon FGFR2 and a few other genes for their strong association signals." (PMID 30875371, 2019). "AA genotype and A allele of P21 and TT genotypes and T allele of FGFR2 were significantly more frequent and were associated with an increased risk of early-onset of breast cancer (95%CI: 2.54 and 1.59; 2.63 and 1.64, respectively)." (PMID 31759353, 2019). "All the results show that individuals with the A allele of FGFR2 rs2981578 presented a greater risk of overall toxicity for CET chemotherapy in breast cancer (adjusted OR = 2.37, 95% CI = 1.55—3.61, P < 0.0001)." (PMID 30359238, 2018). "Among the GWAS SNPs known to be associated with breast cancer risk, notable were two FGFR2 SNPs (rs298175 and rs2981582) that were nominally significant in our breast-colorectal data." (PMID 29698419, 2018). "Single nucleotide polymorphisms (SNPs) in FGFR2 have been associated with an increased risk of ER+ and PR+ breast cancer." (PMID 29455658, 2018). "For instance, fine mapping in the African-American population contributed to the localization of a causal variant in FGFR2, a low penetrance breast cancer susceptibility locus." (PMID 30594178, 2018). "For example, a 2014 study showed association between breast cancer risk and seven breast cancer susceptibility loci (FGFR2, TOX3, STXBP4, SLC4A7, LSP1, 2q35, and 5p12)." (PMID 30249004, 2018). "The association of the fibroblast growth factor receptor 2 gene (FGFR2) polymorphism rs2981582 with breast cancer has been extensively studied, whereas the role of this polymorphism in non-functioning pituitary adenoma (NFPA) has not been elucidated." (PMID 30206133, 2018). "As others have already shown, an intronic single nucleotide polymorphism in FGFR2 rs2981582 was identified as being associated with breast cancer risk." (PMID 30359238, 2018). "FGFR2 is a breast cancer susceptibility gene, and various variants of FGFR2 are significantly associated with the breast cancer risk." (PMID 30359238, 2018). "In breast data, we looked at the transcriptome-wide co-splicing correlations of FGFR2, whose SNP rs2981582 has been associated with breast cancer and for which numerous splicing forms have been found specifically expressed in breast cancer cells lines." (PMID 30545302, 2018). "Single-nucleotide polymorphisms (SNPs) within intron 2 of the FGFR2 gene are associated with breast cancer through allelic FGFR2 upregulation." (PMID 29987267, 2018). "The major finding was a significant association of FGFR4 rs1966265 AA genotype and A allele and FGFR2 rs2981578 A alleles with an increased chemosensitivity in NCT of breast cancer patients." (PMID 30359238, 2018). "We thus studied PRPF8, GRIA1 and FGFR2, which are involved in the regulation of splicing in testis, glutamatergic neurotransmission in brain cortex and susceptibility to breast cancer, respectively." (PMID 30545302, 2018). "FGFR1 amplification is present in 20% of squamous cell lung cancer, 5% of small cell lung cancer and in 10% of breast cancers, FGFR2 amplifications or mutations in about 5% of gastric cancer, FGFR3 mutations in 10-15% of muscle invasive bladder cancer." (PMID 30181810, 2018).
breast carcinoma (continued). "The estimated increases in the risk of BRCAX or high-risk breast cancers from the variants on FGFR2, TOX3, and ESR1 were quite similar across populations (ORs for highest compared to lowest tertile = 2.2 to 2.4)." (PMID 30323354, 2018). "The FGFR2 gene has been identified as a locus associated with an increased risk of developing breast cancer, and a single nucleotide polymorphism in the FGFR2 gene, which enhances RUNX2 binding, increases FGFR2 expression." (PMID 30202094, 2018). "Three independent variants (rs2981578, rs35054928 and rs45631563) of FGFR2 map to transcriptional silencer elements and augment silencer activity resulting in lower FGFR2 expression and increased estrogen responsiveness and breast cancer risk." (PMID 29299175, 2017). "In breast cancer, single nucleotide polymorphisms (SNPs) in FGFR2 were found to be strongly associated with evidence of postmenopausal disease." (PMID 28030802, 2017). "In recent years, the association between mutations in FGFR2 gene and various cancers had been found, such as breast cancer, endometrial cancer, oral squamous cell carcinoma, gastric cancer, and so on." (PMID 27903959, 2017). "A GWAS identified rs2981578 variant in fibroblast growth factor receptor 2 (FGFR2) as one of the highest ranking risk alleles in breast cancer." (PMID 29299175, 2017). "This cluster includes the rs2981579 SNP in the second intron of the FGFR2 gene, which is the SNP with the strongest association with breast cancer in genome-wide analysis." (PMID 28235418, 2017). "This study provides sound evidence for an association between variants in the FGFR2 locus and ER status among breast cancer patients, particularly among patients with HER2-negative disease." (PMID 27764800, 2016). "We thus propose a molecular mechanism by which FGFR2 can confer increased breast cancer risk that is consistent with oestrogen exposure as a major driver of breast cancer risk." (PMID 27236187, 2016). "For example, a cohort study in American population found that the AG/GG genotypes of TNRC9 rs12443621 and the CT/TT genotype of FGFR2 rs2981582 had a decreased risk for death in breast cancer patients." (PMID 26911390, 2016). "Variants regulating FGFR2 (MIM: 176943) have the strongest association with ER+ breast cancer susceptibility identified to date." (PMID 27640304, 2016). "Our findings suggest that reduced FGFR2 expression and signalling is associated with an increase in ER+ breast cancer risk." (PMID 27236187, 2016). "Strong association between the FGFR2 locus and ER status of breast cancer patients was observed (ER-positive n=6211, ER-negative n=2516; rs3135718 OR=1.34 p=5.46×10−12)." (PMID 27764800, 2016). "This region contains well established SNPs in FGFR2 associated with increased risk of breast cancer." (PMID 27708667, 2016). "In contrast, another cohort study in Swedish population found that the AG/GG genotypes of TNRC9 rs12443621 and the AA genotypes of FGFR2 rs2981582 both had increased breast cancer risk." (PMID 26911390, 2016). "The rs2981578 was previously identified as the SNP with the strongest association with overall and ER+ breast cancer in FGFR2 in African Americans, and it was also shown recently by us using AMBER consortium data." (PMID 27708667, 2016). "As oestrogen is the key driver of ER+ breast cancer, our results suggest that an increase in disease risk should be associated with reduced FGFR2 expression." (PMID 27236187, 2016). "The molecular mechanism we propose establishes a link between the inherited risk for breast cancer conferred by germline variation in FGFR2 and environmental effects (oestrogen exposure)." (PMID 27236187, 2016). "The most significant association with overall breast cancer, rs12244041, at P = 2.9 × 10-6, is located over 10 Mb from the well-known breast cancer associated FGFR2 gene and is unlinked to SNPs in this region (r2 = 0.01)." (PMID 27708667, 2016).
breast carcinoma (continued). "It was also reported that some polymorphisms in FGFR2 were associated with breast cancer risk in postmenopausal women." (PMID 27705907, 2016). "Here, we examine the effect of FGFR2 signalling on transcriptional networks in breast cancer and propose a mechanism for FGFR2 risk single-nucleotide polymorphism function." (PMID 27236187, 2016). "The fibroblast growth factor receptor 2 (FGFR2) locus is the ‘top hit’ in genome-wide association studies for breast cancer." (PMID 27236187, 2016). "This is surprising, since most studies reported that the T allele of FGFR2 rs2981582 is associated with increased breast cancer risk." (PMID 26911390, 2016). "This will be of course an obvious next step of our analyses, particularly as pertains to response to hormone therapy and FGFR2 variants in ER+/HER- breast cancer patients." (PMID 27764800, 2016). "The fibroblast growth factor receptor 2 (FGFR2) locus is consistently the top hit in genome-wide association studies for oestrogen receptor-positive (ER+) breast cancer." (PMID 27236187, 2016). "Our study reveals an interesting finding that the GA and AA genotypes of FGFR2 rs2981582 are associated with reduced risk of breast cancer." (PMID 26911390, 2016). "In support of this, genomic studies found that FGFR2 amplifications (1.8%) or mutations (1.3 %) are relatively rare in breast cancer (cBioportal, TCGA)." (PMID 27236187, 2016). "This study indicated the role of TOX3 and FGFR2 as breast cancer susceptibility genes in BRCA1/2-wild-type breast cancer patients from Sardinian population." (PMID 25956309, 2015). "Our results suggest that associations of FGFR2 SNPs with breast cancer were heterogeneous according to intrinsic subtype." (PMID 26421298, 2015). "In conclusion, our study revealed a significant association of FGFR2 intron-2 SNPs with breast cancer risk in Southern Han Chinese and provided strong evidence for differential susceptibility according to intrinsic subtype." (PMID 26421298, 2015). "First, this study confirmed that three SNPs in the second intron of FGFR2 (rs2420946, rs2981579, and rs2981582) were significantly associated with increased risk of breast cancer, which validates earlier GWAS results." (PMID 26421298, 2015). "Mutations in the protein Fibroblast Growth Factor Receptor 2 are associated with breast cancer, so it is of interest to identify compounds which bind it." (PMID 26384374, 2015). "Genome-wide association studies have identified an intronic variant in the FGFR2 gene as a breast cancer susceptibility locus." (PMID 26431494, 2015). "Somatic mutations of FGFR2 have been reported in many cancers, including breast cancers and FGFR2 gene variations confer a risk for breast cancer." (PMID 25831047, 2015). "Specifically, a number of case-control studies have been conducted to investigate the association between FGFR2 polymorphisms located in intron-2 with breast cancer susceptibility in Chinese populations." (PMID 26421298, 2015). "Among the disease-associated genomic regions, TOX3 and FGFR2 genes have been identified as breast cancer susceptibility genes in BRCA1/2-wild-type breast cancer patients from Sardinia." (PMID 25956309, 2015). "This gene has been consistently identified as a risk locus for breast cancer, and 7 SNPs in FGFR2 have had a reported GWAS p-value less than 10−5." (PMID 26157456, 2015). "When we lowered the criterion for significance to p < 10−5, we also identified 11 SNPs in FGFR2, another known breast cancer-associated gene." (PMID 25956309, 2015). "Association of FGFR2 rs2981582, rs1219648, rs2981578 and rs7895676 SNPs with clinicopathological, life style and environmental characteristics of breast cancer patients from North India." (PMID 25333473, 2014).
breast carcinoma (continued). "In this case–control study of sporadic breast cancer in North Indian women we found that the variant genotypes rs2981582C/T, rs1219648A/G, rs2981578A/G and rs7895676T/C of FGFR2 were all significantly associated with increased breast cancer risk." (PMID 25333473, 2014). "Several altered FGFR2 characteristics have been linked with breast tumorigenesis and have shown promising results in studies on breast cancer cell lines and tumors, like amplification and overexpression, mutations, alternative splicing and isoform switching." (PMID 25333473, 2014). "At present, much effort is focussed into targeting additional genetic alterations that drive breast cancer and FGFR2 which has been implicated in different types of human malignancies, including breast cancer, is a likely candidate." (PMID 25333473, 2014). "Two large Genome-Wide Association Studies (GWAS) have identified intron 2 SNPs of FGFR2 to be associated with breast cancer risk, rs2981582 and rs1219648 were the most strongly associated marker SNPs in the two studies respectively." (PMID 25333473, 2014). "For example, fine-mapping in Asian, European, and African-Americans in a FGFR2 associated allele in breast cancer led to better definition of the risk region." (PMID 24901479, 2014). "Genotype and allele frequencies of FGFR2 polymorphisms in sporadic breast cancer cases and controls." (PMID 25333473, 2014). "In haplotype analysis, the FGFR2 rs2981578 G/rs2981582 T/rs1219648 G haplotype was associated with a significantly increased breast cancer risk compared with the rs2981578A/rs2981582 C/rs1219648 A haplotype." (PMID 25333473, 2014). "Chi-square test depicted a significant association for the four FGFR2 variants with overall breast cancer risk (P<0.05)." (PMID 25333473, 2014). "The stage of conditional analysis seems to be analogous to some reported methods, such as the one recently used for fine mapping of the FGFR2 breast cancer risk locus." (PMID 24978468, 2014). "T allele of rs2981582 has been linked with an increased activity of FGFR2 and it has been shown that haplotype marked by this allele associates with a higher level of FGFR2 transcription both in breast cancer cell lines and tumors." (PMID 25333473, 2014). "In conclusion, our study revealed a significant association of FGFR2 intron 2 SNPs with breast cancer risk, as well as their interaction with various clinical parameters revealing their contribution to breast cancer susceptibility among North Indian women." (PMID 25333473, 2014). "FGFR2 was recently identified as a risk factor in breast cancer from several genome-wide association studies for breast cancer." (PMID 23300950, 2013). "We confirmed the association of four SNPs representing three previously reported susceptibility loci with breast cancer risk among Polish women: FGFR2 (rs1219648 and rs2981582), TERT (rs2736098) and 8q24 (rs13281615)." (PMID 24171766, 2013). "The association of FGFR2 variants with breast cancer risk was reported in several studies and is very well documented, with the strongest association observed for rs2981582." (PMID 24171766, 2013). "Given that BRCA2 mutations are more frequent in male breast cancer, FGFR2 levels were expected to be higher in male than in female breast cancer." (PMID 23308200, 2013). "In order to unravel the molecular mechanism of the p.K660N and another recently described somatic breast cancer mutation in FGFR2, p.R203C, we compared the tyrosine kinase activities of breast cancer mutants to that of wt FGFR2." (PMID 23527311, 2013). "Genome-wide association studies identified variants in the fibroblast growth factor receptor 2 (FGFR2) tumor suppressor gene as a genetic risk factor for breast cancer susceptibility." (PMID 23527311, 2013). "The most significant associations were observed for known breast cancer susceptibility regions, rs2420946 (per allele P = 2×10−14) in FGFR2 and rs3803662 (P = 5.4×10−11) near TOX3." (PMID 23544012, 2013).